LTBP3 (latent transforming growth factor beta binding protein 3)
Diseases named in the same sentence as LTBP3 in open-access papers (continued):
Sharing a sentence is not in itself a finding about the gene and the disease.
otosclerosis (1 paper, 2024). Formation of spongy bone in the labyrinth capsule which can progress toward the stapes (stapedial fixation) or anteriorly toward the cochlea leading to conductive, sensorineural, or mixed hearing loss. "Genes that are hyper-methylated in CMV seropositive individuals include LTBP3, a TGF-β component reported in another study, whose mutation/loss-of-function results in hearing loss and otosclerosis." (PMID 39360678, 2024).
prostate carcinoma (1 paper, 2024). A carcinoma that arises from epithelial cells of the prostate gland. "Interestingly, 63 mRNAs, 3 lncRNAs (Linc00662, CHASERR, and lnc-LTBP3-11), 2 miRNAs (miR375-3p and miR92a-1-5p), and 1 piRNA (piR-28004) were found to be highly expressed in prostate cancer tissues and diminished in urinary EVs post-prostatectomy." (PMID 39585046, 2024).
scoliosis (1 paper, 2021). A congenital or acquired spinal deformity characterized by lateral curvature of the spine. "Ltbp3−/− mice also developed craniofacial malformations and curvature of thoracic/cervical vertebrae (scoliosis)." (PMID 34946872, 2021).
Sepsis (1 paper, 2023). Sepsis is defined as life-threatening organ dysfunction caused by a dysregulated host response to infection. "Gene entities exhibiting stronger expression in the SIRS-ranked dataset included CFC1, CT62, lnc-DAAM2-1 and lnc-LTBP3-2 and in the sepsis-ranked dataset included TDRD9, DAAM2, OLFM4 and OLAH." (PMID 38332914, 2023).
tumor (12 papers, 2011 to 2025). "The expression of LTBP3 in the tumour cells significantly associated with distant metastasis and CRC cause of death." (PMID 30679934, 2019). "LTBP3 expression on tumour cells was significantly associated with distant metastasis and CRC cause of death (p = 0.003 and p = 0.005 respectively)." (PMID 30679934, 2019). "LTBP3 is a new cancer target protein, which has a unique function in the regulation of vascularization of tumor cells dependent on angiogenesis." (PMID 34983559, 2022). "Expression of HLAB, protein 14-3-3β, LTBP3, ADAMTS2, JAG2 and NME2 on tumour cells was significantly associated with clinical parameters related to tumour progression, invasion and metastasis." (PMID 30679934, 2019). "Proteins, HLAB, ADAMTS2, LTBP3, JAG2 and NME2 were significantly associated with tumor progression, vascular invasion and distant liver metastasis." (PMID 30679934, 2019). "Six of the 10 (60%) proteins examined using TMA immunohistochemistry, HLAB, protein 14-3-3β, LTBP3, ADAMTS2, JAG2 and NME2, were significantly associated with clinical parameters which have shown to relate with tumor progression, invasion and metastasis." (PMID 30679934, 2019). "Consistent with the role of TGFβ in cancer progression (Padua and Massagué, 2009; Massague, 2012), we show that LTBP3, a protein that regulates TGFβ secretion and bioavailability promotes primary tumor invasion and metastasis." (PMID 24618895, 2014). "Ltbp3 is downregulated in tumor-specific activated mouse T cell populations in comparison to naïve T cells." (PMID 23741501, 2013). "We suggest that MMP-2 contributes to tumor survival by controlling the bioavailability of TGFβ via the processing of LTBPs, such as LTBP-3." (PMID 22238668, 2012). "Expression of HLAB, ADAMTS2, LTBP3, JAG2 and NME2 on tumour cells, was associated with tumour progression and invasion, metastasis and CRC specific survival may serve as potential biomarkers to stratify CRC patients into low and high risk of tumour metastasis." (PMID 30679934, 2019). "LTBP3 was reported to promote early metastasis during cancer cell dissemination by inducing intravasation supporting angiogenic vasculature within developing primary tumours." (PMID 30679934, 2019). "Additionally, by regulating angiogenesis-dependent intracellular perfusion, LTBP3 as a novel tumor target may promote early metastasis in the process of cancer cell proliferation." (PMID 36123690, 2022). "Thus, whether LTBP3 contributes to tumor progression because of its signaling role or its architectural role remains to be elucidated." (PMID 24618895, 2014). "Notable, genes involved in TGF-β signalling (SOS1, SOS2, SMAD5, LTBP3, TGFBR2, IRF7 and CREBZF) were found to be significantly (P<0.01) downregulated in the VEGFA165 tumours." (PMID 22045186, 2011). "LTBP-3 on tumour cells of stage II patients whose tumour did not metastasize and those whose tumour metastasized to the liver were differentially expressed." (PMID 30679934, 2019). "Interestingly, LTBP3 and SNED1 knockdown tumors were characterized by deposition of collagen at the periphery of the tumor forming a thick capsule." (PMID 24618895, 2014). "LTBP3 and SNED1 likely act early in the metastatic cascade by promoting tumor invasiveness." (PMID 24618895, 2014). "Based on our preliminary observations regarding MMP-2 processing of LTBP-3, we hypothesize that osteoblast derived MMP-2 is a key mediator of TGFβ activation in the tumor-bone microenvironment." (PMID 22238668, 2012). "In contrast, knockdown of LTBP3 or SNED1 in LM2 cells did not affect lung colonization, consistent with our finding that these proteins influence tumor cell invasion at the primary site." (PMID 24618895, 2014). "Consistently, the LTBP3 and SNED1 tumors failed to invade the surrounding tissues, suggesting that LTBP3 and SNED1 are promoters of tumor invasiveness." (PMID 24618895, 2014).
cancer (6 papers, 2014 to 2025). A tumor composed of atypical neoplastic, often pleomorphic cells that invade other tissues. "Transcripts of several genes that act as growth inhibitors were less abundant in MtrBTN2, as often seen in cancer contexts, such as FAM107A and LTBP3, which keeps TGF-β in a latent state." (PMID 37816387, 2023). "Finally we show that high expression of LTBP3 and SNED1 correlates with poor outcome for ER−/PR−breast cancer patients." (PMID 24618895, 2014).
skeletal dysplasia (3 papers, 2021). Any Mendelian diseases that affects growth and development of the skeleton. "In summary, we characterized a new, recessively inherited form of skeletal dysplasia in British Shorthair cats and identified a frameshift variant in the LTBP3 gene, c.158delG, as a candidate causative variant." (PMID 34946872, 2021). "LTBP3 was such an ambiguous gene that was previously known for dental and skeletal dysplasia and then noted to be associated with TAAD." (PMID 34906192, 2021). "Our data enable genetic testing to avoid the unintentional breeding of further affected cats and provide a potential spontaneous large animal model for LTBP3-related skeletal dysplasia." (PMID 34946872, 2021).
connective tissue disease (1 paper, 2014). "Mutations in human FBN1, FBN2, LTBP2, LTBP3 and LTBP4 have been associated with connective tissue disease in humans." (PMID 24703491, 2014).
head and neck neoplasm (1 paper, 2023). A benign or malignant neoplasm that affects the anatomic structures of the head and neck region. "Likewise, early-stage head and neck neoplasm patients with high levels of LTBP3 have a poor prognosis for survival." (PMID 36923505, 2023).
LTBP3 also shares sentences with these, for which no sentence is quoted: Acromicric dysplasia (3 papers); multiple myeloma (3); aortic aneurysm (1); aortic stenosis (1); bone disorder (1); cardiopulmonary disease (1); colitis (1); developmental delay (1); diabetes (1); ectodermal dysplasia (1); exfoliation syndrome (1); heart diseases (1); heart failure (1); hematological cancer (1); hepatocellular carcinoma (1); hip osteoarthritis (1); hypertrophic cardiomyopathy (1); inflammatory bowel disease (1); kidney stone (1); liver fibrosis (1); lysosomal storage disorder (1); mitral valve prolapse (1); Myhre syndrome (1); nephronophthisis (1); neurodegenerative disease (1); neurological disorders (1); Nonalcoholic Steatohepatitis (1); Obesity (1); Oligodontia (1); osteogenesis imperfecta (1).
A further 8 diseases each share a sentence with LTBP3 in 1 paper.